UPB1 (beta-ureidopropionase 1)
Description:
Catalyzes a late step in pyrimidine degradation. Converts N-carbamoyl-beta-alanine (3-ureidopropanoate) into beta-alanine, ammonia and carbon dioxide. Likewise, converts N-carbamoyl-beta-aminoisobutyrate (3-ureidoisobutyrate) into beta-aminoisobutyrate, ammonia and carbon dioxide (Probable).
Synonyms: BUP1
Tractability: PROTAC: ubiquitination databases record sites on it.
Target class: Enzyme; Hydrolase
Gene: Protein-coding gene on chromosome 22 (24,494,107 to 24,528,390, forward strand). Ensembl gene ENSG00000100024.
Subcellular location: Cytoplasm
Pathways (Reactome):
Metabolism: Pyrimidine catabolism
Gene Ontology:
Molecular function: beta-ureidopropionase activity; protein homodimerization activity; zinc ion binding
Biological process: beta-alanine biosynthetic process; protein homooligomerization; protein homotetramerization; pyrimidine nucleoside catabolic process; CMP catabolic process; dCMP catabolic process; dUMP catabolic process; in utero embryonic development; liver development; UMP catabolic process
Cellular component: extracellular exosome; cytosol; cytoplasm
Genetic constraint (gnomAD): Loss-of-function variants: 40 observed, 53 expected, observed/expected ratio (o/e) 0.75, 90% interval 0.58 to 0.98. The upper end of that interval is the gene's LOEUF score, 0.98, which puts it in group 4 of 6, group 1 being the genes least tolerant of losing a copy. Missense variants: 499 observed, 533.74 expected, observed/expected ratio (o/e) 0.93, 90% interval 0.87 to 1.01. Synonymous variants: 207 observed, 209.3 expected, observed/expected ratio (o/e) 0.99, 90% interval 0.88 to 1.11.
Homologues: Orthologues: chimpanzee UPB1 (100% identical), macaque UPB1 (98% identical), guinea pig UPB1 (86% identical), mouse Upb1 (86% identical), dog UPB1 (85% identical), rat Upb1 (85% identical), rabbit UPB1 (84% identical), tropical clawed frog upb1 (78% identical), zebrafish upb1 (76% identical), pig UPB1 (71% identical), Drosophila melanogaster pyd3 (64% identical), Caenorhabditis elegans upb-1 (62% identical). Paralogues in human: NIT1 (21% identical), NIT2 (16% identical).
Diseases named in the same sentence as UPB1 in open-access papers:
UPB1 is named in the same sentence as 18 diseases in open-access papers, as found by Europe PMC text mining. Sharing a sentence is not in itself a finding about the gene and the disease. The quoted sentences say what the papers report.
colorectal cancer (2 papers, 2016 to 2022). A primary or metastatic malignant neoplasm that affects the colon or rectum. "Association of UPB1 promoter methylation with worse prognosis of colorectal cancer patients, reported here on two independent groups of patients and in the combined set irrespective of 5-FU treatment, poses a completely novel direction in pharmacogenomics of colorectal cancer." (PMID 27733154, 2016). "Low RRM2 transcript and UPB1 methylation levels present separate poor prognosis factors for colorectal carcinoma patients and should be further investigated." (PMID 27733154, 2016). "In addition, for the treatment of specific tumors, especially the 5-fluorouracil treatment of colorectal cancer, some researchers explored the role of UPB1 in the 5-fluorouracil pathway or fluoropyrimidine-related high toxicity." (PMID 36119068, 2022). "DPYS and UPB1 protein levels were analyzed in a subset of the testing set used for the methylation study, enabling an evaluation of the cascade of methylation, gene, and protein expression levels in colorectal cancer samples." (PMID 27733154, 2016). "We hypothesized that a high UPB1 expression in tumor cells caused by promoter demethylation could exert a negative impact on the colorectal cancer patients response to 5-FU." (PMID 27733154, 2016).
hepatocellular carcinoma (2 papers, 2017 to 2022). A malignant tumor that arises from hepatocytes. "Besides, for cancer patients, UPB1 was screened as a prognostic circulating biomarker or signature for patients with hepatocellular carcinoma, similar to clear renal cell carcinoma." (PMID 36119068, 2022). "In conclusion, we identified a three-gene predictive signature comprised of UPB1, SOCS2 and RTN3 for hepatocellular carcinoma and validated these three genes expression pattern in HCC tissues." (PMID 28717245, 2017).
developmental delay (1 paper, 2012). "This gene is involved in the last step of the pyrimidine degradation pathway and deficiencies in UPB1 have been associated with developmental delay." (PMID 23275889, 2012).
DPYD deficiency (1 paper, 2025). "In particular, UPB1 dysfunction could lead to the accumulation of toxic metabolites, paralleling mechanisms observed in DPYD deficiency." (PMID 40428413, 2025).
MELAS syndrome (1 paper, 2022). MELAS (Mitochondrial myopathy, encephalopathy, lactic acidosis, and stroke) syndrome is a rare progressive multisystemic disorder characterized by encephalomyopathy, lactic acidosis, and stroke-like episodes. "The β-ureidopropionase deficiency which was caused by UPB1 variant can be detected by WES, but the MELAS syndrome requires whole-mitochondrial-genome sequencing to be diagnosed." (PMID 35265567, 2022).
pancreatic cancer (1 paper, 2023). "In the current study, a total of 17 genes with prognostic values have been identified, of which 8 genes (SFXN5, LRRC8E, KCNJ10, UPB1, SLC43A2, SLC38A10, ACCS, and SLC38A5) were identified for the first time in pancreatic cancer." (PMID 37333498, 2023).
propionic acidemia (1 paper, 2016). An organic aciduria caused by the deficient activity of the propionyl Coenzyme A carboxylase and is characterized by life threatening episodes of metabolic decompensation, neurological dysfunction and that may be complicated by cardiomyopathy. "UPB1 is an 5-FU inactivating enzyme, responsible for degradation of pyrimidine bases (uracil and thymine) and its genetic defect causes severe forms of propionic acidemia." (PMID 27733154, 2016).
status epilepticus (1 paper, 2021). Status epilepticus is defined as a continuous seizure lasting more than 30 min, or two or more seizures without full recovery of consciousness between any of them. "The homozygous variant in UPB1 was annotated by the HPO term “status epilepticus” and has been recently published to trigger seizures due to ß-ureidopropionase (UPB) deficiency in a recessive mode of inheritance." (PMID 33789662, 2021). "However, the homozygous likely pathogenic variant in UPB1, recently associated to status epilepticus, has not been linked to SD before." (PMID 33789662, 2021). "The splice variant c.917-1G>A was found homozygous in a 3 months old infant in UPB1, annotated by the HPO term “status epilepticus”." (PMID 33789662, 2021).
cancer (6 papers, 2015 to 2025). A tumor composed of atypical neoplastic, often pleomorphic cells that invade other tissues. "In two sequential studies, hematological and gastrointestinal toxicity rates were analyzed within DPYS and UPB1 genotypes in a cohort of 113 cancer patients (67 of whom experienced severe toxicity, and 46 with good tolerance to FP) and 69 non-cancer individuals." (PMID 37256234, 2023). "Thus far, few studies have explored the relationship between UPB1 and cancer." (PMID 28717245, 2017).
tumor (4 papers, 2015 to 2021). "UPB1 expression (between low expression group and high expression group) was closely correlated with tumor weight (p < 0.0001), histologic grade (p < 0.0001), pathological stage (p < 0.0001), T stage (p < 0.0001) and survival status (p < 0.0001)." (PMID 28717245, 2017). "The expression of UPB1 was found to be correlated with tumor capsule invaded, and no other significant association was observed between UPB1, SOCS2 and RTN3 expression and clinicopathological variables perhaps partly because of the relatively small sample size." (PMID 28717245, 2017). "UPB1 and SOCS2 exhibited lower expression than the corresponding normal tissues, while RTN3 showed a tendency of increase expression in tumor tissues (p = 0.09)." (PMID 28717245, 2017). "The results demonstrated that UPB1 and SOCS2 were downregulated in HCC tissues (UPB1: p < 0.0001; SOCS2: p < 0.0001), while the expression of RTN3 was increased in tumor tissues (p < 0.0001)." (PMID 28717245, 2017). "Our data complies with the results reported by this database, i.e., the highest levels in UPP2, UPB1, and DPYS (the rest of the genes below 25 %) and significantly higher methylation of DPYS in tumor compared with mucosa tissues." (PMID 27733154, 2016). "The present study shows for the first time that only three (DPYS, UPB1, and UPP2) out of 15 evaluated 5-FU genes, are subject to notable methylation in tumor and adjacent mucosa tissues." (PMID 27733154, 2016). "We identified UPB1 (beta-ureidopropionase 1) as negatively correlated with grade in the tumor stroma but not in bulk (METABRIC dataset)." (PMID 34282769, 2021). "RTN3 was upregulated in HCC tumor tissue compared to nontumor tissue (p = 0.00001), while expression of UPB1 in tumor tissue was significantly lower than that in nontumor tissue (p < 0.00001)." (PMID 28717245, 2017). "In the both testing and validation II sets, methylation exceeding the limit of quantitation was detected in DPYS, UPB1, and uridine phosphorylase (UPP2, GeneID: 151531) genes in both tumor and adjacent mucosa samples (DPYS passed the correction for multiple testing)." (PMID 27733154, 2016). "However, we succeeded in developing a three-gene signature including UPB1, SOCS2 and RTN3 based on gene-expression profiles of tumor tissue in this study, and fortunately we have validated this model with two independent GEO microarray datasets produced from different platforms." (PMID 28717245, 2017).
infection (1 paper, 2023). The state of being infected such as from the introduction of a foreign agent such as serum, vaccine, antigenic substance or organism. "After VpAHPND infection, genes in glycolysis, including HK, TPI, and ALDO, and some genes involved in amino acid metabolism, including PAST, MAT, SMOX, and UPB1, showed higher expressions in R20523 family." (PMID 37358285, 2023).
UPB1 also shares sentences with these, for which no sentence is quoted: Acidosis (1 paper); breast carcinoma (1); clear renal cell carcinoma (1); gastric adenocarcinoma (1); liver cancer (1); mitochondrial neurogastrointestinal encephalopathy (1); neurodevelopmental disorder (1).